ELF1 (E74 like ETS transcription factor 1)
Description:
Transcription factor that activates the LYN and BLK promoters. Appears to be required for the T-cell-receptor-mediated trans activation of HIV-2 gene expression. Binds specifically to two purine-rich motifs in the HIV-2 enhancer.
Synonyms: EFTUD1; RIA1
Tractability: PROTAC: ubiquitination databases record sites on it; its protein half-life has been measured.
Gene: Protein-coding gene on chromosome 13 (40,931,242 to 41,061,440, reverse strand). Ensembl gene ENSG00000120690.
Subcellular location: Nucleus
Subcellular location (Human Protein Atlas): Nucleoplasm
Pathways (Reactome):
Gene expression (Transcription): RUNX1 regulates transcription of genes involved in BCR signaling; RUNX1 regulates transcription of genes involved in interleukin signaling
Gene Ontology:
Molecular function: DNA-binding transcription activator activity, RNA polymerase II-specific; DNA-binding transcription factor activity; protein binding; RNA polymerase II cis-regulatory region sequence-specific DNA binding; sequence-specific double-stranded DNA binding; DNA-binding transcription factor activity, RNA polymerase II-specific; sequence-specific DNA binding
Biological process: positive regulation of DNA-templated transcription; positive regulation of transcription by RNA polymerase II; cell differentiation; regulation of transcription by RNA polymerase II; regulation of DNA-templated transcription
Cellular component: nucleoplasm; nucleus; chromatin
Genetic constraint (gnomAD): Loss-of-function variants: 22 observed, 47.87 expected, observed/expected ratio (o/e) 0.46, 90% interval 0.33 to 0.66. The upper end of that interval is the gene's LOEUF score, 0.66, which puts it in group 2 of 6, group 1 being the genes least tolerant of losing a copy. Missense variants: 526 observed, 637.16 expected, observed/expected ratio (o/e) 0.83, 90% interval 0.77 to 0.89. Synonymous variants: 205 observed, 227.37 expected, observed/expected ratio (o/e) 0.9, 90% interval 0.8 to 1.01.
Homologues: Orthologues: chimpanzee ELF1 (99% identical), macaque ELF1 (99% identical), dog ELF1 (93% identical), rabbit ELF1 (92% identical), guinea pig ELF1 (91% identical), mouse Elf1 (89% identical), rat Elf1 (87% identical), pig ELF1 (86% identical), tropical clawed frog elf1 (70% identical). Paralogues in human: ELF4 (37% identical), ELF2 (33% identical), ETV5 (12% identical), FLI1 (12% identical), ERG (12% identical), ETV1 (12% identical), ETV3 (12% identical), ERF (12% identical), ETV4 (12% identical), ELK1 (11% identical), ETS1 (11% identical), ETS2 (11% identical), and 16 more.
Diseases named in the same sentence as ELF1 in open-access papers:
ELF1 is named in the same sentence as 60 diseases in open-access papers, as found by Europe PMC text mining. Sharing a sentence is not in itself a finding about the gene and the disease. The quoted sentences say what the papers report.
breast carcinoma (7 papers, 2012 to 2026). "In conclusion, TFPI-2 mRNA levels were upregulated by miR-494 in MCF-7 breast cancer cells most likely by an indirect association where miR-494 targeted the transcription factors AHR and ELF-1." (PMID 32132611, 2020). "A previous study indicates that in MCF‐7 breast cancer cells, ELF1 plays a transcriptional regulatory role, binding to the human Pygopus2 promoter region and activating its expression, promoting breast cancer cell growth." (PMID 32368853, 2020). "In conclusion, we demonstrated that TFPI-2 levels were upregulated by miR-494 in the breast cancer cell line MCF-7 most likely by an indirect regulation involving the association between miR-494 and the transcription factors AHR and ELF-1." (PMID 32132611, 2020). "ELF1, E74-Like Factor 1 encodes an E26 transformation-specific related transcription factor, and has been shown to help predict the malignant behaviour of non-small cell lung cancer, has been associated with gastric cancer and with endometrial cancer and may modulate breast cancer progression." (PMID 25148247, 2014). "In breast cancer, miR-494 indirectly downregulates TFPI2 by modulating E74-like factor 1 (ELF-1) and aryl hydrocarbon receptor (AHR), promoting tumor growth." (PMID 40361374, 2025). "“All of the mouse and most human mammary tumors also displayed decreased expression of genes known to inhibit cell proliferation, including NFKBIA (IKBalpha), GADD45B, and CDKN1A (p21); transcription-related genes such as CEBP, JUN, JUNB, and ELF1;....”." (PMID 23216862, 2012).
glioma (6 papers, 2020 to 2025). A benign or malignant brain and spinal cord tumor that arises from glial cells (astrocytes, oligodendrocytes, ependymal cells). "ELF1 can activate MEIS1 transcription to promote glioma progression, and it is also involved in the regulation of the relapsing cell state in melanoma and the phenotypic transition." (PMID 40025540, 2025). "The research have shown that FBXO5, which is regulated by transcription factor ELF1, enhances the proliferation, migration, and invasion of gliomas." (PMID 39061113, 2024). "ELF1 exhibits heightened expression in glioma tissues and exhibits a close correlation with WHO grading and patient Karnofsky Performance Status (KPS) scores, suggesting its potential role as a tumor-promoting factor." (PMID 38482016, 2024). "miR‐499a‐5p(+)+ELF1(−) group was compared with control group and miR‐499a‐5p(+)+ELF1(+) group, glioma cell proliferation, VM formation, migration and invasion of glioma cells were clearly decreased." (PMID 32368853, 2020). "The results of this essay demonstrated for the first time the ability of 144aa‐uORF to regulate the formation of glioma cell VM via the ZNRD1‐AS1/miR‐499a‐5p/ELF1/EMI1 pathway." (PMID 32368853, 2020). "Our study confirmed that EMI1 was affected by ELF1 transcriptional regulation and was involved in the regulation of glioma cell VM mediated by ZRND1‐AS1/miR‐499a‐5p/ELF1." (PMID 32368853, 2020). "The role of the 144aa‐uORF\ZNRD1‐AS1\miR‐499a‐5p\ELF1\EMI1 axis in vasculogenic mimicry formation of gliomas was analysed." (PMID 32368853, 2020). "We further constructed 144aa‐uORF(+), ZNRD1‐AS1(−), miR‐499a‐5p up‐regulation and knockdown, ZNRD1‐AS1 and miR‐499a‐5p cotransfection, and miR‐499a‐5p and ELF1 cotransfection into glioma cells." (PMID 32368853, 2020). "Up‐regulation of ELF1 enhanced the VM ability of glioma cell, whereas knockdown of ELF1 resulted in the opposite." (PMID 32368853, 2020). "This study suggests that the 144aa‐uORF\ZNRD1‐AS1\miR‐499a‐5p\ELF1\EMI1 axis takes key part in regulating the formation of vasculogenic mimicry in gliomas and may provide a potential target for glioma treatment." (PMID 32368853, 2020). "Therefore, ZNRD1‐AS1 can be considered as a ceRNA to compete with miR‐499a‐5p, to reduce its negative regulation of ELF1 and promote the formation of VM in gliomas." (PMID 32368853, 2020). "In glioma tissues and cells, the ELF1 expression was detected by qRT‐PCR and Western blot." (PMID 32368853, 2020). "In the current experiment, it was elucidated that ELF1 was largely abundant in gliomas." (PMID 32368853, 2020). "The data argued that ELF1 might have a function in promoting oncogenic genes in gliomas." (PMID 32368853, 2020). "Transcripts of VV-GMCSF-Lact-infected glioma and NB cells that directly correlate with CD50 are enriched with mRNAs controlled by transcription factors ATF2, BRCA1, CREB1, ELF1, TAF1, UBTF, and YY1." (PMID 37998351, 2023). "This study revealed a novel mechanism by which the ZNRD1‐AS1‐144aa‐uORF regulated vasculogenic mimicry in the gliomas via the ZNRD1‐AS1/miR‐499a‐5p/ELF1/EMI1 pathway, providing a new therapeutic strategy for gliomas." (PMID 32368853, 2020). "Our study indicated that ZNRD1‐AS1‐144aa‐uORF and miR‐499a‐5p were underexpressed in glioma tissues and cells, and ZNRD1‐AS1, ELF1 and EMI1 were highly expressed." (PMID 32368853, 2020). "Changes in ELF1 mRNA and protein expression were detected in 144aa‐uORF(+), ZNRD1‐AS1(−) and cotransfection of ZNRD1‐AS1 and miR‐499a‐5p glioma cell lines." (PMID 32368853, 2020). "Real‐time quantitative PCR or Western blot was used to discover the expression of 144aa‐uORF, ZNRD1‐AS1, miR‐499a‐5p, ELF1 and EMI1 in gliomas." (PMID 32368853, 2020). "Notably, ELF1 binds to the promoter region of EMI1 and up‐regulates EMI1 expression, while simultaneously promoting vasculogenic mimicry in glioma cells." (PMID 32368853, 2020).
glioma (continued). "ELF1 expression was increased, and its transcriptional regulation activated EMI1 expression, promoting cell proliferation, migration, invasion and VM formation in gliomas." (PMID 32368853, 2020).
lupus (6 papers, 2014 to 2025). "ELF1 currently plays a regulatory role mainly in autoimmune disorders such as systemic lupus erythematosus, as well as in some cancers." (PMID 40025540, 2025). "In contrast, it was also reported in lupus patients that Elf-1 O-GlcNAcylation–dependent TCR zeta expression was downregulated, which suggests a lack of direct correlation between the mere increase in O-GlcNAcylation and lupus pathology." (PMID 38718861, 2024). "Functionally, it was shown that O-GlcNAcylation and PKC theta induced phosphorylation induces Elf-1 nuclear translocation and transcription of the TCR zeta chain, which is compromised in lupus patients, who express lower levels of TCR zeta." (PMID 38718861, 2024). "Four transcription factors tagged by this analysis are involved in immune-mediated diseases such as systemic lupus erythematosus, inflammatory bowel disease and multiple sclerosis (CFOS, ELF1, ETS1 and NFKB)." (PMID 28793313, 2017). "One point of note is that Elf-1, an important transcription factor of CD3ζ, is dephosphorylated by the increased level of intranuclear PP2A in lupus T cells." (PMID 24864268, 2014). "Dephosphorylated Elf-1 fails to associate with the DNA and initiate transcription of CD3ζ transcription, leading to the increased FcRγ and CD3ζ ratio, favouring subsequent activation of the Syk instead of ZAP-70 pathways in lupus T cells." (PMID 24864268, 2014).
leukemia (4 papers, 2015 to 2022). A malignant (clonal) hematologic disorder, involving hematopoietic stem cells and characterized by the presence of primitive or atypical myeloid or lymphoid cells in the bone marrow and the blood. "ELF1 binds to the HER2 promoter and is upregulated in several cancers (prostate, ovarian, breast, leukemia, lymphoma)." (PMID 37066112, 2022). "We have previously shown a role for ELF1 and RUNX1 in KMT2A-AFF1 leukemias." (PMID 34088716, 2021). "ELF-1 is a predominant cellular factor that binds to the enhancer of the human T-cell leukemia virus type 1 (HTLV-1), the etiological agent of T-cell lymphoma/leukemia." (PMID 26643049, 2015).
melanoma (4 papers, 2008 to 2025). A malignant, usually aggressive tumor composed of atypical, neoplastic melanocytes. "In particular, we observed binding activity of ELF1 at the CDC20 promoter and a reduction in CDC20 upon ELF1 knockdown by siRNA in a melanoma cell line." (PMID 38030698, 2023). "Recent report supported a role of Elf-1 in the development of tumor angiogenesis and showed that targeting of Elf-1 in melanoma tumors resulted in decreased angiogenesis." (PMID 18840277, 2008). "siRNA-mediated knockdown of ELF1 but not GABPA in A375 melanoma cells led to a significant reduction of CDC20." (PMID 38030698, 2023).
colon cancer (3 papers, 2020 to 2024). "ELF-1, binding to the SPINK4 promoter, influenced its expression, and elevated ELF-1 levels were associated with poorer prognosis in colon cancer." (PMID 38747892, 2024). "We also performed survival analysis by combining TF–methylation–lncRNA relationships and found ELF1-cg05372727-LINC00460 could be used to categorize colon cancer patients into low- and high-risk groups." (PMID 33329694, 2020). "Suppression of SPINK4 counteracted ELF-1 overexpression effects, suggesting a therapeutic avenue targeting ELF-1/SPINK4 expression for colon cancer treatment." (PMID 38747892, 2024). "We also found that the ELF1-cg05372727- LINC00460 relationship were prognostic signatures for colon cancer." (PMID 33329694, 2020). "One of the identified TF–methylation–lncRNA relationships (ELF1-cg05372727- LINC00460) was significantly associated with survival in the training set (log rank p < 0.05) and could also be validated in the testing set (log rank p < 0.05), which is the potential prognostic biomarker for colon cancer." (PMID 33329694, 2020).
colorectal cancer (3 papers, 2023 to 2024). A primary or metastatic malignant neoplasm that affects the colon or rectum. "Protein factors that could regulate transcription of SMAD4-213 via AnnoLnc2 predicted binding sites upstream of/overlapping TSS that are expressed in colorectal cancer are CDX2, CEBPB, ELF1, NCOA1, NCOR1, NCOR2 and TFAP4." (PMID 39132157, 2024). "Approximately one-third of colorectal cancer patients show overexpression of TM9SF2 mRNA, which may be regulated by the Ets family transcription factor ELF1." (PMID 39475897, 2024).
lymphoma (3 papers, 2021 to 2025). A malignant (clonal) proliferation of B- lymphocytes or T- lymphocytes which involves the lymph nodes, bone marrow and/or extranodal sites. "In light of these results, we further focused on deregulated miRNAs and their putative interactions with B-cell specific transcription factors SPI1 and ELF-1 attenuated in cHL and also the NF-ĸB inhibitor TNFAIP3 recurrently inactivated in this lymphoma." (PMID 34201504, 2021).
asthma (2 papers, 2021 to 2022). "Moreover, rs72891545, the most significant association signal with asthma exacerbations, has also been predicted to involve the modification of several transcription factor binding sites (ELF1, Myc, Sp4, YY1, Zfx)." (PMID 34442380, 2021).
cervical cancer (2 papers, 2018 to 2019). A primary or metastatic malignant neoplasm involving the cervix. "The reduced expression of ELF1 was proposed as a candidate marker for early diagnosis of cervical cancer." (PMID 31653120, 2019). "ELF1 has also been shown to be required for the proliferation of cervical cancer cells infected with the HPV virus." (PMID 30603056, 2018). "This is evidenced in cervical cancer, where the presence of the human papilloma virus E7 protein inactivates RB1 and allows ELF1 to switch from a repressor of proliferation to an activator of proliferation." (PMID 30603056, 2018).
gastric cancer (2 papers, 2014 to 2025). A primary or metastatic malignant neoplasm involving the stomach. "The level of mRNA expression of ETS family members in gastric carcinoma tissues was also variable with ELF3, ETS2, EHF, ERF and ELF1 being the family members with the highest expression." (PMID 41425714, 2025). "mRNA expression levels of ETS family members in gastric carcinoma tissues were variable, with ELF3, ETS2, EHF, ERF, and ELF1 being the family members with the highest expression." (PMID 41425714, 2025).
metastatic disease (2 papers, 2018 to 2021). "Here we show that ELF1 was the most commonly down-regulated ETS factor in primary prostate tumors, and expression decreased further in metastatic disease." (PMID 30603056, 2018).
non-small cell lung carcinoma (2 papers, 2014 to 2020). A group of at least three distinct histological types of lung cancer, including non-small cell squamous cell carcinoma, adenocarcinoma, and large cell carcinoma. "Interestingly, ELF1 is increased in non‐small cell lung cancer (NSCLC) and further cell metastasis, invasion and VM." (PMID 32368853, 2020).
oral squamous cell carcinoma (2 papers, 2021 to 2023). "SNHG17 has already been confirmed to facilitate cell growth by modulating the miR-384/ELF1 axis in oral squamous cell carcinoma." (PMID 34782005, 2021).
osteosarcoma (2 papers, 2023 to 2024). A usually aggressive malignant bone-forming mesenchymal neoplasm, predominantly affecting adolescents and young adults. "However, ELF1 is not upregulated in other osteosarcomas in this cohort, and its oncogenic role may be limited to rare cases with deregulated expression of the gene." (PMID 39322633, 2024).
prostate carcinoma (2 papers, 2018 to 2023). A carcinoma that arises from epithelial cells of the prostate gland. "ELF1 has also been implicated as a potential tumor suppressor in prostate cancer through analyses of mRNA and DNA copy number alterations from patient samples." (PMID 30603056, 2018). "ELF1 possesses relatively few mutations within this prostate cancer dataset (0.2% samples with ELF1 mutation); however, prostate tumors have a high rate of ELF1 deletions (~15% deep deletion and ~27% shallow deletion)." (PMID 30603056, 2018). "Furthermore, prostate cancer patients with recurrent tumors have decreased ELF1 levels, indicating that ELF1 loss could contribute to prostate cancer progression." (PMID 30603056, 2018). "Further, immunoblots indicate that PrEC cells have much higher ELF1 protein levels than prostate cancer cell lines." (PMID 30603056, 2018). "Gene set enrichment analysis of the TCGA prostate cancer dataset, ranked based on the Pearson correlation of each gene relative to ELF1 mRNA levels, provided further support that ELF1 can function as a tumor suppressor within the prostate." (PMID 30603056, 2018). "This study investigates the role of ELF1 in prostate cancer, providing the first analysis of ELF1's function within the prostate." (PMID 30603056, 2018). "While the prostate cancer and metastasis related gene sets were expected based on our previous genomic and phenotypic assay findings, the ability of ELF1 to potentially affect chemotherapy resistance was novel." (PMID 30603056, 2018). "It has been recently reported that RB1 deletion can promote resistance to chemotherapy in prostate cancer; however, as the ELF1 locus is often lost in these same genomic deletions, we asked if ELF1 depletion might contribute to chemotherapy resistance." (PMID 30603056, 2018). "Furthermore, knockdown of ELF1 increased resistance to docetaxel, a common therapeutic for late-stage prostate cancer." (PMID 30603056, 2018). "Our findings, along with previous studies of ELF1 and its subfamily, suggest that ELF1 has the ability to compete with other expressed ETS factors and is also able to regulate cell fate decisions in prostate cancer cells." (PMID 30603056, 2018). "Analysis of previously published RNA-seq data indicates that ELF1 mRNA levels are highest in normal prostate epithelial cells (PrEC) and immortalized-normal prostate epithelial cells (RWPE-1) as compared to six prostate cancer cell lines." (PMID 30603056, 2018). "However, the contribution of ELF1 deletion to prostate cancer has not been investigated." (PMID 30603056, 2018).
prostate tumors (2 papers, 2018 to 2021). "A direct comparison of 52 prostate tumors with their matched adjacent normal showed that 43 out of 52 samples have decreased ELF1 levels." (PMID 30603056, 2018). "We noted that the ELF1 gene is located 8 mb from RB1, which is known to be deleted in some late stage prostate tumors, and from this dataset we see that ELF1 is often co-deleted with RB1." (PMID 30603056, 2018). "ELF1 was the most commonly down-regulated ETS factor in prostate tumors and even displayed significant down-regulation in tumors lacking genomic deletions." (PMID 30603056, 2018). "The downregulation of ELF1 in ETS fusion positive prostate tumors could allow for increased binding of oncogenic ETS factors at these sites, leading to a subsequent activation of genes involved in various cancerous phenotypes." (PMID 30603056, 2018). "ELF1 is the fourth highest expressed ETS mRNA in normal prostate cells and the decreased expression in prostate tumors is among the most significant in the ETS family." (PMID 30603056, 2018). "However, the large chromosomal deletions found in prostate tumors delete both RB1 and ELF1, and this response would be lost." (PMID 30603056, 2018). "Interestingly, the ELF1 locus is roughly 8 Mb away from RB1 on chromosome 13 and is often co-deleted in prostate tumors." (PMID 30603056, 2018). "Our findings that ELF1 promotes senescence in prostate cells could explain why RB1 is lost due to deletion, rather than mutation in prostate tumors." (PMID 30603056, 2018).